CRP (C-reactive protein)
Diseases named in the same sentence as CRP in open-access papers (continued):
Sharing a sentence is not in itself a finding about the gene and the disease.
psoriasis (continued). "However, inside the PASI subgroups after treatment, we found a positive relation with PLT and CRP in patients with mild psoriasis." (PMID 35053087, 2022). "Among them is C-reactive protein (CRP), whose elevation can be considered an independent risk factor for cardiovascular risk (as levels of CRP decrease, cardiovascular risk lowers) and whose elevation is associated both with psoriasis and psoriatic arthritis." (PMID 34829740, 2021). "Brepocitinib has since done well in both phase I and phase II trials, whereby it reduced C-reactive protein (CRP) by almost 50% and almost completely resolved skin inflammation in psoriasis patients (75% reduction in their psoriasis symptoms [PASI75] in ∼80% of subjects)." (PMID 34290741, 2021). "Furthermore, psoriasis severity (assessed by PASI score and CRP) was negatively associated with the intake of extra virgin oil, fruits, nuts, fish or seafood, vegetables and legumes, whereas it was positively correlated with red meat intake." (PMID 33499118, 2021). "As an inflammatory factor, CRP participates with various cytokines in the immune response and may play an important role in promoting the development of psoriasis." (PMID 34372872, 2021). "Inflammation biomarkers that have been previously used in psoriasis patients include serum levels of C-reactive protein (CRP), haptoglobin, complement 3 (C3), C4, TNF-α, IL-6, IL-8, IL-12, elafin, neutrophil-lymphocyte ratio (NL), and platelet-lymphocyte ratio (PL)." (PMID 32881431, 2020). "Therefore, we first stratified patients with psoriasis by systemic inflammation using median hs-CRP levels (hs-CRP >1.8 mg/L)." (PMID 33104056, 2020). "We excluded 34 (17%) participants suffering from acute infections and 12 patients suffering from chronic diseases (bronchial asthma n = 5, recurring bronchitis n = 4, recurring otitis n = 1, psoriasis n = 1, recurring urinary tract infections n = 1) from analysis of CRP and ANC." (PMID 32154197, 2020). "Moreover, the possible contribution of FGF21 to the development and maintenance of inflammation are underlined by the correlation observed in our research between the concentration of FGF21 in patients with psoriasis and the CRP value." (PMID 31847236, 2019). "CRP elevation is attributable (at least partially) to psoriasis inflammation." (PMID 31275060, 2019). "Only 17%–45.7% of patients with psoriasis present with an increased CRP concentration." (PMID 31336842, 2019). "A direct correlation between CRP and psoriasis severity was found." (PMID 31275060, 2019). "Multivariate regression analysis showed that psoriasis (β = 12.339, 95% CI 0.601, 24.078), CRP elevation (β = 3.893, 95% CI 0.113, 7.672), and average grade of sacroiliitis (β = 3.855, 95% CI 1.960, 5.750) were positively associated with inflammatory SPARCC score of SIJ." (PMID 30947732, 2019). "Patients with uncontrolled psoriasis and PsA have exacerbated CRP levels." (PMID 29587639, 2018). "A diet and exercise intervention was also found to reduce concentrations of TNF-α, IL-6, IL-8, C-reactive protein and monocyte chemoattractant protein 1, which may contribute to improvement of psoriasis." (PMID 29680995, 2018). "Furthermore, several studies showed positive correlations between CRP levels and severity of skin involvement in psoriasis." (PMID 30363704, 2018). "In addition, serum CRP values and leukocyte counts correlated negatively and significantly with disease duration in all psoriasis patients." (PMID 29967791, 2018). "The authors showed that all the patients with psoriasis had higher levels of CRP than controls." (PMID 29619128, 2018). "That is why, this study evaluates how CRP is altered in patients with psoriasis and whether these markers correlate with the duration and severity of the disease." (PMID 29967791, 2018). "YKL-40 could be considered as a biomarker of inflammation in psoriasis and is more sensitive than CRP or WBC; however, the issue needs further and more detailed investigation." (PMID 28932021, 2017).
psoriasis (continued). "YKL-40 could be considered as a useful biomarker of inflammation in psoriasis and is more sensitive than CRP or WBC." (PMID 28932021, 2017). "MetS in conjunction with psoriasis was associated with high levels of CRP, significantly higher than in control subjects without MetS." (PMID 29068430, 2017). "Psoriasis patient with MS showed higher level of many inflammatory cytokines in serum, such as CRP, TNF-α, IL-17, which may exacerbate the cutaneous inflammatory state so as to promote the progression of psoriasis." (PMID 29390261, 2017). "Moreover, the systemic inflammatory marker C-reactive protein (CRP) has been found to be elevated in patients with psoriasis." (PMID 29065479, 2017). "The clinical usefulness of C-reactive protein determinations in cardiovascular disease in the general population has been questioned among patients with pre-existing inflammatory conditions such as psoriasis." (PMID 29295598, 2017). "The level of CRP can also serve as a marker of psoriasis severity." (PMID 28097156, 2016). "Plasma levels of SAA and CRP have been reported to be up-regulated in psoriasis patients." (PMID 27401543, 2016). "We show that serum CRP, detected by the high sensitivity test (hs-CRP, one marker of systemic inflammation) is elevated in psoriasis patients compared to controls even after adjusting for several variables including age, gender, race, BMI, and current smoking status." (PMID 27448600, 2016). "Serum CRP concentrations correlate with psoriasis severity and interventions that decrease the CRP concentration may decrease also psoriasis severity." (PMID 26767505, 2016). "Elevated serum and salivary CRP levels have been reported in patients with psoriasis." (PMID 21151525, 2010). "Additionally, a meta-analysis of seven randomized controlled trials indicated that oral probiotics could improve psoriasis and reduce serum CRP levels, consistent with previous findings." (PMID 40353222, 2025). "In addition, CAR was more predictive of psoriasis severity than CRP, albumin, and ESR." (PMID 40172389, 2025). "Specifically, we aimed to examine the relationships between these apolipoprotein levels and psoriasis severity, as measured by the Psoriasis Area and Severity Index (PASI), as well as disease duration and associated systemic inflammation, assessed by serum C-reactive protein (CRP) levels." (PMID 40137160, 2025). "Moreover, CRP was significantly lower in CTCL than in psoriasis and drug-induced groups." (PMID 38337339, 2024). "Similarly, in a study, secukinumab was shown to reduce CRP levels in psoriasis." (PMID 37731441, 2023). "Therefore, given the association between CRP and psoriasis, we used CRP as a marker in an attempt to validate weak validity not reflected by efficacy indicators." (PMID 37967075, 2023). "In addition to psoriasis treatment monitoring by imaging techniques, as well as C-reactive protein, erythrocyte sedimentation rate, fibrinogen, zinc, and copper levels, resistin could also be a valuable predictive marker." (PMID 37895330, 2023). "Moreover, serum CRP level is one of the factors indicating the severity of psoriasis." (PMID 33961663, 2021). "A positive correlation between C-reactive protein and monocyte-to-high-density-lipoprotein ratio leads to the suggestion that monocyte-to-high-density-lipoprotein ratio might be a reliable parameter in psoriasis during the follow-up." (PMID 31889591, 2020). "Therefore, we could proclaim that elevated levels of proinflammatory CRP and leptin and decreased levels of anti-inflammatory adiponectin reflect an ongoing inflammatory process in patients with psoriasis." (PMID 26166954, 2015). "When evaluating if psoriasis disease severity (PASI score) was associated with inflammatory-related and CV disease-related proteins in the blood, it was noted that PASI strongly correlated with serum levels of MDC (r = 0.59, p < 0.001) and CRP (r = 0.27, p = 0.001)." (PMID 23965158, 2013).
psoriasis (continued). "This subgroup was characterized by longer disease duration, higher frequency of r-axSpA, enthesitis, and psoriasis, as well as elevated MASES, CRP, ASDAS-CRP, and BASDAI scores." (PMID 41553409, 2026). "In patients with psoriasis, MG concentration in serum negatively correlated with the disease severity indices BSA and PASI, CRP (C-reactive protein) concentration, and the inflammatory response indicators SII and AISI." (PMID 39982364, 2025). "In the patients, MG concentration correlated negatively with psoriasis disease severity indicators (BSA and PASI), C-reactive protein (CRP) concentration, and inflammatory response indicators (SII and AISI)." (PMID 39982364, 2025). "Elafin levels were correlated with psoriasis severity, as measured by the PASI score and with inflammatory markers CRP and ESR." (PMID 40650250, 2025). "Moreover, the significantly higher CRP concentrations and ESR in psoriasis patients suggest that systemic inflammation may play a role in the more frequent development of metabolic comorbidities in association with psoriasis." (PMID 38378928, 2024). "Outliers were identified for age, BMI, CRP, DAPSA, DAS28, ESR, HAQ, PGA, psoriasis, sex, SJC, TJC, and treatment line." (PMID 39467905, 2024). "Psoriasis area and severity index (PASI), blood count, and C-reactive protein (CRP) levels were attained at each timepoint." (PMID 38127137, 2024). "The DAS28, sex, ESR, psoriasis, axial disease, disease duration, treatment line, HAQ, DAPSA, SJC, and CRP were moderate." (PMID 39467905, 2024). "It is worth noting that patients with comorbid psoriasis exhibited significantly higher ASDAS-CRP levels (p = 0.028) and serum CRP levels (p = 0.019)." (PMID 38966536, 2024). "Levels of serum CRP and TNFα in NLRP3 genotypes of psoriasis patients were significantly different (P < 0.00001)." (PMID 38965465, 2024). "In this study, the proportion of Th17 cells in peripheral blood was significantly increased in the patients with psoriasis compared with the healthy controls, and the Th17 cell proportion positively correlated with NLR, ESR, CRP, and PASI." (PMID 37596509, 2023). "This has been observed in different studies, evidencing a correlation between CCR4+ CCR5+ CD8 TEFF with serum level of C-reactive protein (CRP) and with (psoriasis area and severity index) PASI score in patients with psoriatic disease." (PMID 37958689, 2023). "The values of C-reactive protein (CRP), platelet to lymphocyte ratio (PLR), neutrophil to lymphocyte ratio and monocyte to lymphocyte ratio decreased in parallel with psoriasis area and severity index (PASI) at weeks 12 and 52 of treatment." (PMID 36769622, 2023). "Further, the values of the CRP, NLR and PLR were correlated with each other and decreased after treatment with ADA or IFX in patients with psoriasis." (PMID 36769622, 2023). "Studies investigating C-reactive protein (CRP), NLR, PLR, monocyte-lymphocyte ratio (MLR), and RDW have also been conducted in psoriasis patients." (PMID 37731441, 2023). "In this study, the serum concentrations of IL-10 in the psoriasis group were decreased compared to the healthy group, and the IL-10 concentrations negatively correlated with NLR, ESR, CRP, and PASI." (PMID 37596509, 2023). "We herein analyze the transition of the NLR, MLR, PLR or CRP during the treatment with TNF-α inhibitors, IFX, ADA and CZP in patients with psoriasis and tried to determine which of the parameters can act as biomarkers reflecting the treatment response." (PMID 36769622, 2023). "Testing the CRP and PLR during treatment with TNF-a inhibitors in patients with psoriasis is relevant and useful for monitoring treatment responses to these biologics." (PMID 36769622, 2023). "Accordingly, in patients with psoriasis and PsA, a correlation between CD8 TEMRA-expressing CD69 early activation markers and the level of serum CRP was observed." (PMID 37958689, 2023).
psoriasis (continued). "The study outcomes included change values in Psoriasis Area and Severity Index (PASI) (at 3 months, 6 months, and end of follow-up)/Dermatology Life Quality Index (DLQI)/Psoriasis disability index (PDI)/C-reactive protein (CRP), and adverse events." (PMID 37967075, 2023). "After administering low-dose IL-2 for psoriasis, it also decreased the inflammatory indicators of disease activity, including the leukocyte count, neutrophil count, ESR, CRP, and NLR in serum after treatment." (PMID 37596509, 2023). "As a result, the IL-17/IL-10 ratio was increased in the psoriasis group compared to the healthy group, and it positively correlated with NLR, PLR, ESR, CRP, and PASI." (PMID 37596509, 2023). "Our aim is to investigate the relationship of hematological parameters and C-reactive protein (CRP) with the presence and severity of the disease in patients with psoriasis." (PMID 37731441, 2023). "The serum levels of CRP, NAD, AGEs, and RAGE appear to be promising potential biomarkers of psoriasis." (PMID 35625870, 2022). "Before therapy, in patients with mild psoriasis (PASI I) gal-3 positively correlated with HGB, RBC, and CRP levels." (PMID 35053087, 2022). "According to PASI subgroups, in patients with mild psoriasis, PON1 significantly positively correlated with WBC, CRP, PLT, Chol and AST activity." (PMID 35888704, 2022). "We found higher serum CRP levels in patients with psoriasis and NMSC than in patients with psoriasis alone." (PMID 36293148, 2022). "Increase in white blood cell count, C-reactive protein (CRP), and several cytokines such as IFN-γ were found in patients with psoriasis; however, these markers alone lack sensitivity and specificity for evaluating the severity of disease." (PMID 35813465, 2022). "Hb, hemoglobin; RDW, red cell distribution width; MCV, mean corpuscular volume; CRP, C-reactive protein; PASI, Psoriasis Area and Severity Index; CV, cardiovascular." (PMID 33776570, 2021). "In the multivariable analysis, the following variables were included: receiving nutritional advice (group N), age, full- or part-time employment, psoriasis, disease duration, use of TNF inhibitors, concomitant treatments, BMI, patient VAS global, and CRP." (PMID 34416917, 2021). "One study investigating Bifidobacterium infantis 35624 across IBD, psoriasis, and chronic fatigue syndrome (CFS) showed that it induced a reduction in CRP across all three conditions." (PMID 32698454, 2020). "Patients were assessed with BMI, 66/68 joints count, Leeds enthesitis index, psoriasis body surface area (BSA), questionnaires and CRP at baseline, 3 and 6 months." (PMID 30635024, 2019). "The psoriasis patients with PASI > 10 had significantly higher RDW and CRP than healthy controls and patients with PASI ≤ 10 (p < 0.001 for all)." (PMID 29967791, 2018). "When compared to healthy controls, psoriasis patients had significantly higher MCV, RDW, CRP, disulphide, disulphide/native thiol, and disulphide/total thiol values (p < 0.001 for all)." (PMID 29967791, 2018). "When compared to healthy controls, psoriasis patients had significantly higher MCV, RDW, C-reactive protein (CRP), disulphide, disulphide/native thiol, and disulphide/total thiol (p < 0.001 for all)." (PMID 29967791, 2018). "In conclusion, observed inflammatory and anti-inflammatory markers (CRP, adiponectin, leptin, resistin, and Lp-PLA2) are involved in both pathogenesis of MS and pathogenesis of psoriasis." (PMID 28097156, 2016). "The clinical severity was assessed by standardized psoriasis area and severity index (PASI) score and c-reactive protein (CRP) levels, and the quality of life was evaluated by dermatology life quality index (DLQI)." (PMID 27165166, 2016). "Significant improvement of erythrocyte sedimentation rate, ultrasensitive CRP, BSA, PASI, Nail Psoriasis Severity Index, Physician Global Assessment and psoriatic arthritis screening and evaluation questionnaire was also observed at that time." (PMID 26633680, 2015).
psoriasis (continued). "PASI, Psoriasis Area Severity Index; CRP, C-reactive protein; PREDIMED, PREvención con DIeta MEDiterránea." (PMID 25622660, 2015). "CRP was reduced in patients from all three categories, TNF-α was reduced in patients with CFS and psoriasis, and IL-6 was reduced in those with UC and CFS all as compared to placebo." (PMID 27417751, 2015). "The severity of psoriasis was by assessed by standardized Psoriasis Area and Severity Index (PASI) score and C-reactive protein (CRP) levels." (PMID 25622660, 2015). "CRP is an acute phase reactant, widely recognized as a non-specific systemic inflammatory biomarker, and was proven to be elevated in cases of active psoriasis." (PMID 40563994, 2025). "Similarly, HS patients have been found to have higher systemic inflammatory markers (C-reactive protein, circulating leukocyte counts) and pro-inflammatory cytokine levels (TNF-α) than other chronic inflammatory diseases like psoriasis." (PMID 40004643, 2025). "Since it has been reported that patients with psoriasis have higher MCV and C-reactive protein (CRP) levels compared to healthy subjects, MCV may be related to chronic inflammation that is crucial for the development of liver fibrosis in MASLD." (PMID 40649054, 2025). "Additionally, HS patients have been found to have higher systemic inflammatory markers (C-reactive protein, circulating leukocyte counts) and pro-inflammatory cytokine levels (TNF-α) than other chronic inflammatory diseases like psoriasis." (PMID 40004643, 2025). "Firstly, elafin levels were correlated with psoriasis severity, as measured by the PASI score and with inflammatory markers like C-reactive protein (CRP) and the erythrocyte sedimentation rate (ESR), indicating a strong association between inflammation and disease severity." (PMID 40650250, 2025). "Elevated levels of CRP and IL-6 have been found to precede the onset of T2DM and CVD, suggesting that inflammatory dermatoses like psoriasis and LP may serve as early markers for cardiometabolic screening and intervention." (PMID 40870891, 2025). "Another parameter explored by our group, C-reactive protein (CRP), is an acute-phase molecule correlated with many conditions and not specific to psoriasis." (PMID 40332589, 2025). "The bidirectional association between OSA and psoriasis suggests a common systemic inflammatory pathway The activity of IL-7, TNF, IL-6, and C-reactive protein was significantly increased in OSA patients, and the increase of this activity was also significantly correlated with psoriasis." (PMID 40166062, 2025). "Moreover, patients with severe disease course, as indicated by the Psoriasis Area Severity Index (PASI) > 10, showed significantly higher levels of CRP than those with mild disease." (PMID 40584532, 2025). "CRP primarily reflects acute-phase hepatic responses and is not consistently elevated in all psoriasis patients, particularly in the absence of systemic flares." (PMID 40722707, 2025). "Despite psoriasis being a systemic inflammatory skin disease, conventional inflammatory markers such as CRP, ESR, etc., do not exhibit elevated levels." (PMID 39467182, 2024). "Baseline age, PsA duration, CRP level, and swollen joint count, but not psoriasis duration/severity, weakly correlated with baseline vdH-S score." (PMID 37787903, 2024). "Laboratory tests, including complete blood count (CBC) and C-reactive protein (CRP), were performed to rule out systemic illnesses and infections, such as streptococcal pharyngitis, which is known to precipitate psoriasis flares, and hepatitis." (PMID 39364528, 2024). "A 6–8-week oral administration of Bifidobacteria infantis 35624 in psoriasis patients not receiving any anti-psoriatic treatment significantly decreased the plasma levels of C-reactive protein and TNF-α." (PMID 37895330, 2023). "The C-reactive protein and PLR might act as biomarkers reflecting a treatment response to TNF-α inhibitors in patients with psoriasis." (PMID 36769622, 2023).